PGR (progesterone receptor)
Diseases named in the same sentence as PGR in open-access papers (continued):
Sharing a sentence is not in itself a finding about the gene and the disease.
breast cancer (continued). "Estrogen receptor (ER), progesterone receptor (PR), and human epidermal growth factor receptor 2 (HER2) are three key biomarkers used to classify breast cancer into four major molecular subtypes based on their expression levels." (PMID 40983817, 2025). "Another surrogate marker for distinguishing luminal A-like from luminal B-like breast cancers, progesterone receptor expression, is also an independent prognostic factor for HR+/HER2- breast cancer, particularly in premenopausal women." (PMID 40557948, 2025). "In contrast, the Shanghai Breast Cancer Survival Study, a prospective cohort study, showed that regular postdiagnosis exercise was associated with a lower risk of all-cause mortality and recurrence/disease-specific mortality in women with ER and progesterone receptor-negative breast cancer." (PMID 40066446, 2025). "Researchers have also used multiplex ddPCR to detect common gene indicators in breast cancer, achieving highly consistent results with immunohistochemistry (IHC) detection by simultaneously detecting HER2, ESR1, PUM1, and PGR genes." (PMID 40042093, 2025). "Regarding subtype, 54 patients (80.6%) had ER-positive breast cancer, 45 patients (67.2%) had PgR-positive breast cancer, and 57 patients (85.1%) had HER2-negative breast cancer." (PMID 41091279, 2025). "The upregulated differentially expressed breast cancer stem cell markers included CD56/NCAM1, POU5F1, PROCR/CD201, ITGA6, and the downregulated were ESR1, PGR, HER2/ERBB2, ABCG2, CD44, CD24, EPCAM, and CDH1." (PMID 40690373, 2025). "Erb-b2 receptor tyrosine kinase 2 (ERBB2), progesterone receptor (PGR), and estrogen receptor (ER) are three key receptors frequently used to classify breast cancers." (PMID 40141415, 2025). "This review explores the state-of-the-art in virtual staining for breast cancer biomarkers (HER2, PgR, ER and Ki-67) and benchmarks several models on public datasets." (PMID 40603634, 2025). "Currently, estrogen receptor (ER), progesterone receptor (PR), and human epidermal growth factor receptor 2 (HER2) markers are widely used in routine clinical practice for breast cancer classification and therapeutic guidance." (PMID 40901118, 2025). "Approximately 15% to 20% of breast cancer cases are classified as triple-negative breast cancer (TNBC), which lacks estrogen receptor (ER), progesterone receptor (PR), and HER2 expression." (PMID 40282270, 2025). "Tissue expression biomarkers in breast cancer, such as estrogen receptor (ER), progesterone receptor (PR), and human epidermal growth factor receptor 2 (HER2), are extensively used as tumor-specific markers to guide breast cancer therapy." (PMID 38672729, 2024). "In PLA using FFPE tissue in 25 breast cancer cases, the ERα PLA score was positively correlated with the ERα or PgR immunohistochemistry score." (PMID 39246627, 2024). "Triple-negative breast cancer (TNBC) cells are devoid of estrogen receptors (ERs), progesterone receptor (PRs), and human epidermal growth factor receptor 2 (HER2), and it (TNBC) counts for about 10–15% of all breast cancers." (PMID 38892472, 2024). "Conversely, IHC markers for breast cancer (BC) include GATA3, GCDFP-15, TRPS1, estrogen receptor (ER), progesterone receptor (PR), and human epidermal growth factor receptor 2 (HER2)." (PMID 38905573, 2024). "TNBC is aggressive and lacks estrogen receptor (ER), progesterone receptor (PR), and HER2/neu receptor expression, limiting targeted therapy options that are effective for other breast cancer subtypes." (PMID 39463536, 2024). "ERα is a major determinant of tumor growth in about 80% of breast cancers in which it controls cell cycle genes such as cyclin D1 (CCND1) and differentiation genes such as the progesterone receptor gene (PGR) and the ERα coding gene itself (ESR1)." (PMID 37989525, 2024). "Five independent prognostic factors for breast cancer-specific survival (BCSS) were identified: tumor size, N status, LODDS, progesterone receptor status, and histological grade." (PMID 38637725, 2024).
breast cancer (continued). "TNBC, which lacks the expression of estrogen receptor (ER), progesterone receptor (PR), and HER2, accounts for only 20% of all breast cancers, yet is responsible for a relatively large proportion of breast cancer deaths." (PMID 39353903, 2024). "One successful example is to distinguish the type of breast cancer by the expression of human epidermal growth factor receptor 2 (HER2), estrogen receptor (ER), and progesterone receptor (PR) in breast cancer tissues." (PMID 38763973, 2024). "Breast cancer segmentation is based on the levels of human epidermal growth factor receptor 2 (HER2), progesterone receptor (PR) and estrogen receptor (ER) by immunohistochemical staining." (PMID 38877505, 2024). "The immunohistochemical expression of hormone receptors such as the estrogen receptor (ER), progesterone receptor (PR), and human epidermal growth factor receptor 2 (HER2), is a widely accepted and commonly used classification system for breast cancer." (PMID 38540304, 2024). "For example, Dekkers and colleagues developed protocols for long-term culturing of all major breast cancer subtypes (TNBC, estrogen-positive/progesterone receptor (PR)-positive, and HER-2-positive)." (PMID 39408832, 2024). "Based on the expression of three important BC markers, namely, the progesterone receptor, estrogen receptor, and human epidermal growth factor receptor 2, BC can be categorized into four types: luminal A, luminal B, HER2 (+), and triple-negative breast cancers." (PMID 38404689, 2024). "Cyclin E1 (CCNE1) and Progesterone Receptor (PGR also known as PR), represent two well known breast cancer genes present in the PAM50 signatures that are used to delineate the different molecular subtypes of breast cancer." (PMID 39003292, 2024). "Pathological substitution of ‘intrinsic subtype’ using the status of the estrogen receptor (ER), progesterone receptor (PgR), HER2 and Ki-67 is prevalent in clinical practice for breast cancer." (PMID 37934318, 2024). "In contrast to breast cancer cells in in vitro culture, the expression of CHI3L2 in tumors was highest in tumors positive for estrogen receptor (ER) and progesterone receptor (PR) and lowest in HER2 positive tumors." (PMID 39557919, 2024). "TNBC is a subtype of breast cancer observed in HBC and CMT that lacks the expression of three key receptors: the estrogen receptor (ER), progesterone receptor (PR), and human epidermal growth factor receptor 2 (HER2)." (PMID 39796003, 2024). "Particularly in MCF7 cells, increased levels of H3K4ac were observed near the promoters of genes such as ESR1 (estrogen receptor α), PGR (progesterone receptor) and GREB1 (growth regulation by estrogen in breast cancer 1), an early estrogen-responsive gene." (PMID 39456765, 2024). "Breast cancer cells were reported to significantly proliferate in DEHP- and MEHP- treated groups, and the protein levels of isoform A of the progesterone receptor (PR) and nuclear levels of PR in the cells also increased." (PMID 38341560, 2024). "On the other hand, the migratory subtype showed shared characteristics with Luminal A and Normal-like classification, as they had low expression of known breast cancer markers such as ESR1, PGR and ERBB2." (PMID 38892065, 2024). "Breast cancer’s intrinsic subtypes, identified by the expression of the proliferation marker Ki-67, human epidermal growth factor receptor 2 (HER2), progesterone receptor (PR), and estrogen receptor (ER), reveal the intricacy of the disease." (PMID 38785990, 2024). "In day-to-day practice, based on the immunohistochemical expression of the estrogen receptor (ER), progesterone receptor (PR), and human epidermal growth factor receptor 2 (HER2), breast cancer is classified into various molecular subtypes." (PMID 39099998, 2024).
breast cancer (continued). "Triple‐negative breast cancer (TNBC), which lacks expression of classically estrogen receptor (ER) and progesterone receptor (PR) and human epidermal growth factor receptor‐2 (HER‐2) amplification, makes up 15–20% of all breast cancer cases." (PMID 39690134, 2024). "Although genes that are particularly specified for breast cancer, such as ESR1, PGR, HER2, EGFR, and AR are highly correlated in mRNA-protein expression, nearly 50% of gene expressions are not consistent with their protein levels both in tumors and cell lines." (PMID 37408196, 2023). "The expression of the estrogen receptor (ER), progesterone receptor (PR), and human epidermal growth factor receptor 2 (HER2) in breast cancer cells is critical for determining tumor aggressiveness and targeting therapies." (PMID 37568628, 2023). "Elaborate investigation of the molecular mechanisms revealed the significance of estrogen receptor (ER), progesterone receptor (PR), and human epidermal growth factor receptor (HER2) in breast cancer." (PMID 37700842, 2023). "How it works: The monoclonal antibody trastuzumab is labeled with 89Zr to identify breast cancer cells overexpressing the HER2 receptor, as is the case in luminal B (ER/PgR+, HER2+) and HER2+ (ER/PgR−, HER2+) breast cancer subtypes." (PMID 36165348, 2023). "Immunohistochemical expression status of four biomarkers; hormone receptors [estrogen receptor (ER), progesterone receptor (PR)], human epidermal growth factor receptor (HER2), and Ki-67, are key determinants of breast cancer molecular subtyping." (PMID 36797689, 2023). "Given the observed difference with breast cancer tumor subtypes, we investigated DNAm AA with respect to gene expression levels of ESR1 (estrogen receptor 1) and PGR (progesterone receptor) in these women." (PMID 36991516, 2023). "These include nuclear estrogen receptor (ER), progesterone receptor (PR) and surface membrane bound human epidermal growth factor receptor 2 (HER2), with 85–90% of breast cancer overexpressing one or more of these receptors." (PMID 37583424, 2023). "Using immunohistochemistry (IHC), the three hormone receptors for estrogen receptor (ER), progesterone receptor (PR), and human epidermal growth factor receptor-2 (HER2) are first identified in breast cancer tumors to determine the type of breast cancer." (PMID 37383162, 2023). "Based on the expression status of the estrogen receptor (ER-a), progesterone receptor (PR) and human epidermal growth factor 2 receptor (HER2/ERBB2), breast cancer is classified as luminal A, luminal B, HER2 positive and TNBC." (PMID 37365643, 2023). "Approximately 12% to 17% of breast cancer cases are TNBC, defined as tumors that lack expression of estrogen receptor (ER), progesterone receptor (PR), and human epidermal growth factor receptor type 2 (HER2)." (PMID 38125789, 2023). "Prior to the advent of microarrays, breast cancer classification was determined by the status of markers such as BRCA, estrogen receptor (ER), progesterone receptor (PR) and HER2." (PMID 37269418, 2023). "Between subtypes of breast cancer patient tumors, TNBC/basal tumors showed significantly higher OGT expression than estrogen/progesterone receptor-expressing luminal A/B breast tumors." (PMID 37231419, 2023). "From the purpose of treatment, breast cancer can be divided into three subtypes: human epidermal growth factor receptor 2 (HER2) positive, androgen and progesterone receptor (ER, PR) positive, and triple-negative." (PMID 37284316, 2023). "In addition, a significant and inverse association has also been observed between quantitative measurements of ERBB2 gene copy number and ER/progesterone receptor (PR) protein expression levels in breast cancer, which may further explain the relative resistance of HR+/HER2+ tumors to ETs8." (PMID 37258523, 2023). "In our results, heterogeneous distribution of the expression of breast cancer-related genes (ESR1, PGR, ERBB2, and MKI67) was observed." (PMID 37759508, 2023).
breast cancer (continued). "Approximately 15–20% of breast cancers overexpress HER2, and nearly half of HER2+ breast cancers also express hormone receptors (HRs), such as estrogen receptor positive (ER+) and/or progesterone receptor positive (PR+)." (PMID 37754530, 2023). "Together with hormone receptors (HR) status, based on estrogen (ER) and progesterone receptor (PR) expression, HER2 status is standard for the diagnosis of breast cancer (BC)." (PMID 38137385, 2023). "Among the early breast cancer patients, the marker expression was compared to clinical parameters such as patient age, HER2 status, estrogen (ER) and progesterone receptor (PR) status, lymphangioinvasion, KI 67 label index, and tumor grade." (PMID 36831613, 2023). "For instance, multiple bacterial taxa exhibited distinct prevalence when comparing various subtypes of breast cancer, characterized by their human epidermal growth factor receptor 2 (HER2), estrogen receptor (ER), and progesterone receptor (PR) status." (PMID 38292482, 2023). "Among them, TNBC with negative immunohistochemical results for estrogen receptor (ER), progesterone receptor (PR), and HER2 in the breast cancer tissue is a highly heterogenous disease with an extremely poor prognosis." (PMID 37275874, 2023). "Triple-negative breast cancer (TNBC), which lacks estrogen receptor (ER), progesterone receptor (PR), and human epidermal growth factor receptor 2 (HER2), is a highly aggressive subtype of breast cancer." (PMID 37752122, 2023). "Most breast cancer patients differentially expressed three common biomarkers, i.e., estrogen receptor (ER), human epidermal growth factor receptor 2 (HER2), and progesterone receptor (PR)." (PMID 37240198, 2023). "Finally, core biopsies of 652 breast cancer patients undergoing neoadjuvant chemotherapy, examined via immunohistochemistry, revealed that the intensity and expression of Lcn-2 were significantly related to estrogen and progesterone receptor status, as well as with the histological tumor type." (PMID 37958332, 2023). "Although each individual tumor is identified by the overall gene expression, the status of estrogen receptor (ER), progesterone receptor (PR), and human epidermal growth factor receptor 2 (HER2) in breast cancers define their treatment approach." (PMID 36140539, 2022). "TNBC lacks the estrogen receptor (ER), the progesterone receptor (PR), and the human epidermal growth receptor 2 (HER2) and accounts for 10–20% of all breast cancer cases." (PMID 35884900, 2022). "In breast cancer cells, E3 ligase BRCA1 and CUEDC2 have been shown to regulate PGR protein stability." (PMID 35244538, 2022). "Growing evidence supports this novel therapeutic target for the treatment of triple-negative breast cancers that lack ERα, progesterone receptor, and human EGF receptor 2, and ERα-positive breast cancers, which are resistant to conventional endocrine therapy." (PMID 37435447, 2022). "We generated a stable MCF7 breast cancer cell line expressing a SNAP-GFP-PRB (SNAP (trademark), green fluorescent protein (GFP) and Progesterone Receptor Isoform B (PRB))." (PMID 35881789, 2022). "Triple-Negative Breast Cancers (TNBCs), a breast tumor type defined by lack ofestrogen receptor, progesterone receptor and human epidermal growth factor receptor 2 (HER-2) accounts for about 10-15% of the total breast cancer." (PMID 36909691, 2022). "The association with Ki-67 is of considerable clinical relevance, however concordance with ER, PgR, HER2 positivity and histological grade remains critical for breast cancer treatment." (PMID 35300617, 2022). "There were significant differences in stage_N (P = 0.014), histological grade (P = 0.001), ER status (P < 0.001), PgR status (P < 0.001), NACT regimens (P = 0.032) and NACT efficacy (P = 0.037) between patients with HER2-negative and HER2-low breast cancer." (PMID 36605428, 2022). "ER, PgR and the Ki-67 index were indicated as independent predictors for breast pCR in ER+, HER2− breast cancer patients." (PMID 35093083, 2022).
breast cancer (continued). "Based on the estrogen receptor (ER), progesterone receptor (PgR), and human epidermal growth factor receptor 2 (HER2), four main major breast cancer subtypes have been identified, including luminal A and luminal B, basal-like and HER2-enriched." (PMID 35093083, 2022). "Triple-negative breast cancer (TNBC) is a dangerous BC subtype that lacks three widely used diagnostic markers, including human epidermal growth factor receptor 2 (HER-2), progesterone receptor (PR), and estrogen receptor (ER), accounting for approximately 15%–20% of BC presentations." (PMID 35300426, 2022). "Breast cancer can be classified into different subgroups, which are primarily on the basis of human epidermal growth factor receptor 2 (HER2), progesterone receptor expression (PR), Ki-67 value, and estrogen receptor (ER)." (PMID 36203428, 2022). "Our previous studies demonstrate that these important drug targets in breast cancer, ESR1, PGR, HER2, EGFR, and AR have a high similarity in mRNA and protein variations in both tumors and cell lines." (PMID 36360219, 2022). "In our study, on the basis of univariate and multivariate logistic analyses, ER expression, PgR expression, and the Ki-67 index were screened as independent prognostic predictors of achieving breast pCR or overall pCR in ER+, HER2− breast cancer patients." (PMID 35093083, 2022). "Using additional biomarkers such as progesterone receptor (PR) and human epidermal growth factor receptor 2 (HER2), breast cancer is further classified as luminal A, luminal B, basal-like, and HER2-positive." (PMID 36232567, 2022). "According to the indicators oestrogen receptor (ER), progesterone receptor (PR), human epidermal growth factor receptor-2 (HER2), and Ki67, breast cancer is subdivided into luminal A, luminal B, HER2-positive, and triple-negative breast cancer (TNBC)." (PMID 35165254, 2022). "TNBC lacks expression of estrogen receptor (ER), progesterone receptor (PR) or HER2/neu gene amplification, and accounts for 11-15% of breast cancers in the US." (PMID 36703796, 2022). "Estrogen receptor (ER), progesterone receptor (PR), and human epidermal growth factor receptor 2 (HER2) are shared breast cancer biomarkers, and the classification of breast cancer is mostly centered on them." (PMID 35154452, 2022). "Features of the tumor and the status of the estrogen receptor (ER), progesterone receptor, and human epidermal growth factor receptor 2 (HER2) in the tumor, affect the treatment of breast cancer." (PMID 36420288, 2022). "The breast cancer cell line MDA-MB-231 is ‘basal’ type and triple negative, i.e. missing three markers: ER, progesterone receptor (PR) and HER2/Neu oncogene." (PMID 35382578, 2022). "PCGF2 in luminal breast cancer cells positively regulates the promoter activities of ER-α (estrogen receptor-α) and PGR (progesterone receptor) by suppressing SUMOylation." (PMID 36407101, 2022). "The expression of estrogen receptor-α (ER), progesterone receptor (PR), and HER2 are important determinants for treatment and management, with about 70% of breast cancers being ER-positive (ER+ve)." (PMID 35267559, 2022). "TNBC is a clinically aggressive type of breast cancer with poor survival, compared with other breast cancer types, including HER2-positive, oestrogen receptor (ER)-positive and progesterone receptor (PR)-positive." (PMID 36386788, 2022). "In breast cancer, studies have revealed that SPOP targets substrates such as c-Myc, steroid receptor coactivator 3 (SRC-3) and progesterone receptor (PR), thus functioning as a tumor suppressor." (PMID 36360288, 2022). "Clarifying menopause status and measurement of ER/PgR is mandated for all cases of invasive breast cancer, as recently outlined in the 5th ESMO International Consensus for advanced and local breast cancers in addition to the recent RxPONDER trial." (PMID 35887614, 2022).